BGN (biglycan)
Diseases named in the same sentence as BGN in open-access papers (continued):
Sharing a sentence is not in itself a finding about the gene and the disease.
colorectal cancer (23 papers, 2013 to 2026). A primary or metastatic malignant neoplasm that affects the colon or rectum. "Our study demonstrates that Biglycan (BGN) positive cancer-associated fibroblasts (BGN + Fib) serve as a driver in colorectal cancer (CRC)." (PMID 38654221, 2024). "In colorectal cancer, upregulated biglycan expression was associated with an increased risk of both lymph node and distant metastasis." (PMID 25593993, 2014). "BGN may have diagnostic and prognostic value for ovarian, prostate, gastric, and colorectal cancers, according to studies." (PMID 37842511, 2023). "Previous studies have found that the up-regulation of BGN in a variety of solid tumors and its potential diagnostic and prognostic value in ovarian cancer, prostate cancer, gastric cancer and colorectal cancer." (PMID 35096572, 2021). "In colorectal cancer, BGN downregulation in CAFs markedly reduced cancer cell migration and proliferation." (PMID 41465449, 2025). "Studies have found that high expression of BGN in colorectal cancer 33, GC 34, prostate cancer 35, lung cancer 36, endometrial cancer 37, and melanoma 38, and linked expression to poor prognosis." (PMID 36632455, 2023). "The authors highlighted that the overexpressed BGN, RCN3, TAGLN, MYL9 and TPM2 in cancer-associated fibroblast as potential prognostic biomarkers for patients with colorectal cancers." (PMID 36172359, 2022). "Previous study has identified BGN as one of CNV-mRNA-protein correlated molecules in colorectal cancer patients with liver metastasis by integrative analysis of multi-omics data." (PMID 35096572, 2021). "The expression of BGN mRNA was dramatically increased in stage I colorectal cancer samples in the TCGA database." (PMID 32050430, 2020). "In breast, lung and colorectal cancers, high biglycan expression was correlated with poor prognosis by meta-analyses using PrognoScan." (PMID 27295191, 2016). "For example, in gastric and colorectal cancer as well as in pancreatic adenocarcinoma, BGN expression was found to be correlated with poor prognosis." (PMID 24223213, 2013). "In several solid malignancies, including pancreatic cancer, breast cancer, colorectal cancer, and head and neck squamous cell carcinoma, BGN has been reported to promote tumor cell phenotypes, such as proliferation, migration, and immune suppression, thereby contributing to tumor progression." (PMID 41465449, 2025). "Recent studies reported that BGN might be a crucial marker of fibroblasts in breast cancer and colorectal cancer." (PMID 36772945, 2023). "NF-κB may serve a crucial factor at the early stage of colorectal cancer progression, and we demonstrated that it may play a crucial role in the regulation of BGN gene expression." (PMID 32050430, 2020). "In addition, we also confirmed that BGN mRNA was elevated most significantly in colorectal cancer compared to healthy control in the TCGA database." (PMID 32050430, 2020). "CM of all breast and colorectal cancer cell lines enhanced versican and biglycan expression." (PMID 25593993, 2014). "In recent years, it has been gradually found that BGN is closely related to the occurrence and development of various malignant tumors, such as endometrial cancer, ovary cancer, pancreatic adenocarcinoma, esophageal squamous cell carcinoma, colorectal cancer, and prostate cancer." (PMID 36110576, 2022). "BGN, RCN3, TAGLN, MYL9, and TPM2 were identified as fibroblast-specific biomarkers with a poor prognosis in colorectal cancer." (PMID 35785171, 2022). "BGN and MYL9 were also found to be fibroblast-specific markers of poor prognosis in colorectal cancer." (PMID 36589754, 2022). "Nevertheless, secretome experiments show that nearly all breast and colorectal cancer cell lines induce both α-SMA, versican and biglycan in CAFs, which implies TGF-β1-like effects." (PMID 25593993, 2014).
colorectal cancer (continued). "Furthermore, we also propose that BGN (biglycan) is one of the potential TLR4 ligands that are highly elevated and involved in the epigenetic silencing of Siglec ligands in colorectal cancer." (PMID 32050430, 2020). "For example, BGN up-regulation was significantly correlated with poor tumor differentiation, lymph node metastasis, and distant metastasis in colorectal cancers, but not with other clinicopathological factors." (PMID 24681892, 2014).
breast carcinoma (22 papers, 2014 to 2025). "Recently, some studies have shown that abnormal expression of the BGN protein is closely associated with tumor metastasis and a poor prognosis for cancers, including GC and breast cancer." (PMID 35273678, 2022). "To further explore associations implicating a potential role for BGN in human breast cancers, we interrogated data from TCGA using the Gepia online software." (PMID 35053617, 2022). "Our study is first to report that VCAN rs11726, independently or interacting with BGN polymorphisms, is associated with shoulder pain or disability in breast cancer survivors." (PMID 34162438, 2021). "However, opposite effects have been implicated in case of breast cancer, indicating that BGN mediates the antiproliferative effects of embryonic mesenchyme inducing partial breast cancer reversion." (PMID 38786104, 2024). "In dogs, BGN upregulation has been identified in cancer-associated stroma of malignant CMTs, both in proteomic and transcriptomic approaches, and these results were consistent with human breast cancer studies." (PMID 39462388, 2024). "Furthermore, high BGN expression was also associated with reduced disease-free survival of breast cancer patients." (PMID 35053617, 2022). "Additionally, clinical data showed that high BGN expression was significantly associated with poorer overall survival of breast cancer patients compared to low BGN expression." (PMID 35053617, 2022). "In the current study, high expression of stromal biglycan associated with a worse outcome in human breast cancers, indicating that tumor stromal biglycan might play a role in cancer progression." (PMID 33966638, 2021). "Finally, proteins highly correlating with both simple and complex carcinoma were mainly related to pathways including ECM organisation, cell adhesion, cell motility, and cell migration, including ECM-associated proteins previously associated with mammary cancer, such as BGN and FN1." (PMID 39462388, 2024). "However, the underlying role of BGN in breast cancer and BCSCs remains elusive." (PMID 35053617, 2022). "Furthermore, BGN was positively associated with ANGPT2 expression in human breast cancers." (PMID 33966638, 2021). "Higher expression levels of BGN, FN1, COL11A1, and SPTBN1 are linked to poorer overall survival in breast cancer patients is noticeable." (PMID 40898538, 2025). "Survival analysis showed that higher levels of BGN, FN1, COL11A1, and SPTBN1 are linked to poorer OS in patients with breast cancer." (PMID 40898538, 2025). "For instance, in breast cancer, high BGN expression is negatively correlated with CD8+ T cell infiltration and is associated with an immunosuppressive tumor microenvironment." (PMID 41465449, 2025). "Both FN1 and BGN correlate positively in a transcriptomic study between canine mammary carcinomas and human breast cancer." (PMID 39462388, 2024). "EVs from CMT cell lines exhibit distinct protein profiles reflecting malignancy state, allowing us to identify potential biomarkers for canine mammary carcinomas, such as biglycan." (PMID 39462388, 2024). "BGN was one of the most over-represented proteins in the carcinoma EV signature and shows potential as an EV-biomarker for canine mammary tumours." (PMID 39462388, 2024). "In breast cancer tissues, the expression of BGN was significantly lower when compared to normal breast tissue." (PMID 36972253, 2023). "Data on BGN expression in human breast cancer is scant and contradictory, and little information is available for human BGN protein expression in vivo using an antibody against the full length of the protein." (PMID 36972253, 2023). "BGN expression was significantly higher in the stroma than in the epithelium in pancreatic, colorectal, ovarian and breast cancers, implying the stromal origin of BGN." (PMID 36772945, 2023). "To establish a potential role of BGN in brain metastases in breast cancer patients, we analyzed publicly available gene expression data." (PMID 37456245, 2023).
breast carcinoma (continued). "BGN was the most significantly upregulated gene in dormant breast cancer cells in our model and was downregulated in actively growing brain and lung metastases as compared to the primary tumors in patients." (PMID 37456245, 2023). "For the first time, we have demonstrated that regulation of BGN in BCSCs mediated breast cancer metastasis." (PMID 35053617, 2022). "In contrast, we observed that BGN attenuation in BCSCs decreased tumorigenic phenotypes, migration and invasion suggesting its oncogenic function in breast cancer." (PMID 35053617, 2022). "Altogether, these results suggested that BGN plays a role in maintaining BCSC properties in breast cancer." (PMID 35053617, 2022). "Here, we performed RNA sequencing on two distinct co-existing BCSC populations, ALDH+ and CD29hi CD61+ from PyMT mammary tumor cells and detected upregulation of biglycan (BGN) in these BCSCs." (PMID 35053617, 2022). "In breast cancers, BGN was found to play a role in establishing a breast cancer supportive ECM environment, and a separate study suggested that high BGN levels were associated with immune-mediated suppression of tumour progression and better prognosis." (PMID 34449016, 2021). "Higher mRNA and protein expression of biglycan correlated with worse distant metastasis-free survival of breast cancer patients." (PMID 33966638, 2021). "Our findings demonstrated that stromal biglycan alters breast cancer microenvironment, and deletion of stromal biglycan enhances the efficacy of chemotherapy treatment." (PMID 33966638, 2021). "In the present study, we focused on the functional role of stromal biglycan in breast cancer microenvironment using biglycan knockout (Bgn KO) mice." (PMID 33966638, 2021). "Collectively, these studies point to a pro-tumorigenic role of biglycan proteoglycan in both mesenchymal (osteosarcoma) and epithelial (colon and breast carcinomas) malignancies." (PMID 34917515, 2021). "We found associations between VCAN rs11726 A>G genotype and BGN (rs743641 (251A>T) – rs743642 (318G>T)) – VCAN rs11726 (1429A>G) inferred allele combinations, and shoulder pain/disability among women following breast cancer treatment." (PMID 34162438, 2021). "In a mouse model of breast cancer with tumor-bearing mice, knockout of biglycan in the stroma inhibited metastasis to the lung, impaired tumor angiogenesis and normalized tumor vasculature by repressing TNF-α and angiopoietin 2 (ANGPT2) signaling." (PMID 34917515, 2021). "FN1 and BGN were targeted here due to their expression pattern being similarly up-regulated in human breast cancers." (PMID 30205506, 2018). "Bischof and colleagues have made a case for breast cancer cell normalization by biglycan isolated from embryonic mesenchyme in vitro." (PMID 25927296, 2014). "In line with our findings, biglycan has been previously shown to induce breast cancer cell normalization, as indicated by the induction of acinar spheroid formation and reduced proliferation, to induce cell cycle arrest in pancreatic cancer cell lines, and to inhibit growth of bladder cancer cells." (PMID 37456245, 2023). "BGN protein expression is reduced in breast cancer tissue, compared to normal tissue." (PMID 36972253, 2023). "Upregulation of biglycan (BGN; also known as proteoglycan-1 and dermatan sulfate PG-1) has been reported in multiple types of solid tumors, including prostate, pancreatic, gastric, colon, endometrial, bladder and breast cancers." (PMID 36765749, 2023). "With our results, further studies may investigate the use of BGN as a biomarker or as a prognostic factor in breast cancer." (PMID 36972253, 2023). "Another explanation for the lower levels of BGN protein expression in breast cancer tissue may be related to the full-length monoclonal antibody that was used here." (PMID 36972253, 2023). "Interestingly, the predictive value of BGN in breast cancer as a whole and in TNBC cohorts seemed to be contradictory." (PMID 36772945, 2023).
breast carcinoma (continued). "Similarly, lung tissues from mice injected with BGN depleted ALDH+ CSCs showed smaller metastatic foci compared to mice injected with control sgRNA ALDH+ BCSCs, indicating BGN is playing an important role in BCSC mediated breast cancer metastasis." (PMID 35053617, 2022). "Finally, ALDH+ and CD29hi CD61+ BCSCs depleted of BGN exhibited reduced metastasis, suggesting BGN as a potential therapeutic target in BCSCs to inhibit breast cancer metastasis." (PMID 35053617, 2022). "Therefore, to evaluate the role of BGN in breast cancer metastasis, we performed experimental metastasis assays." (PMID 35053617, 2022). "However, the role of soluble BGN in breast cancer progression and metastasis is unclear; therefore, future studies are required to delineate the specific contributions of intracellular and soluble BGN." (PMID 35053617, 2022). "Furthermore, biglycan expression was higher in the tumor stroma compartment compared to the tumor epithelial compartment of human breast cancers." (PMID 33966638, 2021). "Breast cancer patients with high biglycan expression had worse distant metastasis-free survival." (PMID 33966638, 2021). "Furthermore, co-expression analysis by cBioPortal showed that BGN was positively associated with PECAM1 and ANGPT2 expression in human breast cancers." (PMID 33966638, 2021). "BGN was positively correlated with ANGPT2 expression in human breast cancers." (PMID 33966638, 2021). "Our results suggest that targeting stromal biglycan may yield a potent and superior anticancer effect in breast cancer." (PMID 33966638, 2021). "Taken together, these results suggest that biglycan may be involved in tumor angiogenesis and destabilization of tumor blood vessels in human breast cancers." (PMID 33966638, 2021). "Although, no studies to date have demonstrated their roles in breast cancer, BGN and DCN have been implicated in the development and progression of endometrial, bladder, colon, blood or lung cancers." (PMID 34162438, 2021). "Additionally, we investigated the therapeutic efficacy of targeting stromal biglycan combined with conventional chemotherapy in breast cancer." (PMID 33966638, 2021). "Biglycan may represent a promising candidate to potentiate the efficacy of anticancer therapies in breast cancer." (PMID 33966638, 2021). "Biglycan was found to be upregulated in human breast cancers compared to normal mammary glands." (PMID 33966638, 2021). "Finally, siRNA knockdown of biglycan mRNA and protein in embryonic fibroblasts abrogated their ability to normalize breast cancer cells or reduce their growth in vitro." (PMID 25927296, 2014). "Therefore, the objective of this study is to verify the immunohistochemical expression of BGN in breast cancer biopsies compared to normal breast tissue using a validated monoclonal antibody and two digital imaging methods of analysis: D-HSCORE and deep learning neural network image analysis." (PMID 36972253, 2023). "Therefore, the correlations between BGN levels and immunotherapy response were analyzed in multiple cancers, including urothelial cancer, basal cell carcinoma, non‐small cell lung cancer, clear cell renal cell carcinoma (ccRCC) and breast cancer." (PMID 36772945, 2023). "Based on the analysis of scRNA-seq and bulk RNA-seq data, we built and validated a cancer fibroblast-related risk signature consisting of five genes (BGN, LUM, CCL19, CEBPD, and ID3) that may be utilized as an independent prognostic indicator for breast cancer patients." (PMID 36510567, 2022). "Finally, loss of BGN in ALDH+ and CD29hi CD61+ BCSCs showed decreased metastatic potential, suggesting BGN serves as an important therapeutic target in BCSCs for treating metastasis of breast cancer." (PMID 35053617, 2022). "Thus, BGN could be an important therapeutic target in breast cancer patients for the treatment of breast cancer metastasis." (PMID 35053617, 2022). "However, the function of stroma biglycan in breast cancer is still unclear." (PMID 33966638, 2021).
breast carcinoma (continued). "Lastly, associations between SNPs in ACAN/BGN/DCN genes and treatment characteristics may have an undetermined influence on our findings and should be explored in greater depth with breast cancer risk." (PMID 34162438, 2021). "Therefore, BGN may prove useful as a specific EV biomarker for canine mammary carcinomas." (PMID 39462388, 2024). "Collectively, these data demonstrate that BGN plays a role in maintaining BCSC properties and is a potential therapeutic target to inhibit breast cancer metastasis." (PMID 35053617, 2022). "To further validate our results from PyMT tumors, we also utilized a human luminal breast cancer cell line, MCF-7, and its sorted BCSCs, CD24−/CD44+ for determining BGN expression." (PMID 35053617, 2022). "However, the roles of biglycan in breast cancer microenvironment remain unclear." (PMID 33966638, 2021). "Pearson’s correlation coefficients showed that Biglycan mRNA expression was positively correlated with both PECAM1(Spearman’s correlation = 0.45) and ANGPT2 (Spearman’s correlation = 0.4) levels in human breast cancers." (PMID 33966638, 2021). "Here, we provide evidence showing that targeting stromal biglycan alters the tumor microenvironment and enhances intratumoral infiltration of CD8+ T cells in a TNBC mouse model (E0771 breast cancer)." (PMID 33966638, 2021). "Carcinoma EVs shared 60 over-represented proteins, including ECM proteins involved in cell adhesion, motility, wound healing and maintenance of cell shape (FN1, BGN, HAPLN1), which have all been previously identified in human breast cancer and canine mammary cancer studies." (PMID 39462388, 2024). "Importantly, increases in COL8A1, BGN, COL11A1, POSTN, MMP11 and SORCS2 and decreased LTBP4, PCOLCE2, LRRC17 and SDK1 have been identified in CAS and CAFs from human breast cancer and are consistently perturbed in stroma of canine and human mammary cancer." (PMID 37391533, 2023). "Further analysis of non-matched primary breast tumors and breast cancer metastases from different organs revealed a significantly downregulated BGN expression in lung and brain metastases, and a tendency towards reduced BGN expression in liver metastases." (PMID 37456245, 2023). "In our study, biglycan was only expressed in tumor blood vessels of mouse breast cancers, and not in normal mammary gland tissue." (PMID 33966638, 2021).